IGFBP1 (insulin like growth factor binding protein 1)
Diseases named in the same sentence as IGFBP1 in open-access papers (continued):
Sharing a sentence is not in itself a finding about the gene and the disease.
gastric cancer (continued). "A negative correlation was found between VSTM2L and CIMP, and a CIMP-related gene signature comprising six genes (VSTM2L, CST6, SLC7A2, RAB3B, IGFBP1, and EVX2) stratified gastric cancer patients into high‐ and low-risk groups with distinct prognoses." (PMID 35155565, 2021). "Expression of IGFBP3/4/7 was significantly elevated in gastric cancer samples, whereas IGFBP1 expression was decreased in normal tissues." (PMID 34745945, 2021). "Notably, IGFBP1 demonstrated significant differences in expression among the stomach cancer cell lines." (PMID 38700505, 2024). "IGFBP1 is expected to become an important therapeutic target for stomach cancer." (PMID 38700505, 2024). "In view of this, IGFBP1 is expected to become a new target for the treatment of stomach cancer." (PMID 38700505, 2024). "Finally, we identified IGFBP1 as a crucial factor in the prognostic model and verified its role in promoting the malignant phenotype of stomach cancer cells through functional experiments." (PMID 38700505, 2024). "Previous studies have shown that IGFBP-1 in gastric cancer cells can influence cell migration." (PMID 34692659, 2021). "A study of 11 gastric cancer cell lines demonstrated that IGFBP1 expression levels were extremely low in all cell lines, whereas IGFBP2 and IGFBP4 were expressed in 10 and 9 cell lines, respectively, and IGFBP3, IGFBP5, and IGFBP6 were expressed in half of all cell lines." (PMID 34745945, 2021). "In conclusion, we systematically analyzed the transport protein IGFBP1–7 in gastric cancer." (PMID 34745945, 2021). "Based on the TCGA cohort, we integrated clinical factors such as age, stage, N stage, SPCS1, IGFBP1 and TSPYL2 to construct a nomogram to enhance survival prediction for patients with stomach cancer." (PMID 38700505, 2024). "In gastric cancer cell lines AGS and MKN45, IGFBP1 was knocked down for three days, followed by treatment with 2 μg/ml Tunicamycin to induce ER stress, for a duration of 24 hours." (PMID 38700505, 2024). "The expression of EIF4E, EXOSC1, IARS1, IGFBP1, and SPCS1 was found to be upregulated in stomach cancer cell lines, while TSPYL2 and TUBB2A showed downregulated expression." (PMID 38700505, 2024). "In this study, we found that IGFBP1 knockdown in gastric cancer cells AGS and MKN45 amplifies the UPR under ER stress, suggesting that IGFBP1 plays a critical role in ER stress adaptability." (PMID 38700505, 2024). "In gastric cancer cells IGFBP-1 has been reported as a target of miR-519a, but paradoxically when miR-519a is overexpressed (and IGFBP-1 downregulated), cell migration and invasion are inhibited, suggesting a possible tumor-promoting role for IGFBP-1 in this cancer." (PMID 35597813, 2022). "Notably, KISS1, TIMP2, MMP11, IGFBP1, and EGFR have been reported to be involved in the metastasis of gastric cancer." (PMID 32117443, 2020).
colorectal cancer (13 papers, 2005 to 2024). A primary or metastatic malignant neoplasm that affects the colon or rectum. "By analyzing 196 chemorefractory colorectal cancer patients with available plasma samples, we showed that high concentrations of IGFBP-1 and/or IGFBP-2 were associated with shorter overall survival." (PMID 38136368, 2023). "Lower concentrations of the insulin–like growth factor binding protein-1 (IGFBP-1) and elevated concentrations of insulin or C-peptide have been associated with an increase in colorectal cancer risk (CRC)." (PMID 22950808, 2012). "In addition, IGFBP-1, which was reduced in Prx4KO mice, is inversely associated with colorectal cancer in human subjects." (PMID 36978925, 2023). "Similarly, lower pre-diagnosis plasma concentrations of IGF-binding protein 1 (IGFBP-1) have been linked to increased mortality in patients with colorectal cancer treated by surgical resection." (PMID 24905030, 2014). "IGFBP-1 mRNA expression profile data of peripheral blood in colorectal cancer (CRC) patients were downloaded and analyzed from Gene Expression Omnibus database." (PMID 38246959, 2024). "Because there have been few studies on the role of IGFBP-1 in the development of colorectal cancer and the molecular mechanisms of action." (PMID 38246959, 2024). "Kim et al22 also confirmed that overexpression of IGFBP1 promotes liver metastasis in nude mice experiments with colorectal cancer cell lines." (PMID 33164330, 2020). "Lycopene supplementation increases the circulating levels of IGFBP-1 and IGFBP-2 in high-risk populations of colorectal cancer patients, suggesting that lycopene might reduce the risk of colorectal cancer and potentially the risk of other cancers, such as prostate and breast cancer." (PMID 23970935, 2013). "By contrast, IGFBP1 and IGFBP4 protein showed medium or low expression in several tumors such as pancreatic cancer and colorectal cancer." (PMID 37088808, 2023). "We observed in our study the highest IGFBP-1, IGFBP-2 and IGFBP-3 mRNA expression in Dukes’ stage D colorectal cancer cells, having the lowest level IGFBP-6." (PMID 34290976, 2021).
endometrial cancer (13 papers, 2007 to 2025). Primary or metastatic malignant neoplasm involving the endometrium (mucous membrane that lines the endometrial cavity). "Bariatric surgery can lower glucose levels and insulin and insulin-like growth factor-binding protein 1 (IGFBP-1); in addition, this surgery can improve insulin sensitivity in obese women and decreases inflammatory endometrial cancer risk biomarkers." (PMID 35269674, 2022). "C-peptide, insulin, C-reactive protein, leptin, IL-1Ralpha, and IL-6 decreased significantly, while SHBG, IGFBP1, and adiponectin increased significantly in weight-loss interventions in endometrial cancer." (PMID 31440472, 2019). "As a transcription factor, overexpression of KLF12 in endometrial cancer cell lines significantly repressed proliferation and secretion of pro-survival factors such as insulin-like growth factor binding protein-1." (PMID 24555920, 2014). "Genetic variation in IGF2 and IFGBP3 may influence the risk of endometrial cancer in Caucasians, but IGFBP1 SNP rs4619 showed no such association." (PMID 27144430, 2016). "In addition, genetic variants in IGFBP-3, not IGFBP-1 is associated with the risk of endometrial carcinoma." (PMID 22720981, 2012). "First, it has been reported that increased plasma concentrations of hormones such as GnRH and PlGF (secreted by the placenta), and proteins such as IGFBP1 and PLAC-1 are correlated to the development of endometrial cancer." (PMID 30921436, 2019). "In endometrial cancer cell cultures, metformin treatment lowers secretion of insulin-like growth factor (IGF-1), downregulates expression of insulin receptor and IGF-1R, inhibits phosphorylation of IGF-1R, and increases expression of insulin-like growth factor-binding protein 1 (IGFBP-1)." (PMID 30211120, 2018).
lung carcinoma (12 papers, 2016 to 2024). "Our data provide a new molecular mechanistic connection between FOXO3a and miRNA155-5p, as well as the subsequently induced IGFBP1-mediated mechanism underlying the anti-lung cancer effects of β-elemene." (PMID 30209296, 2018). "Testing the gene expression difference among patients with high-risk and low-risk score revealed a total of 14 genes with significant differences between the two groups, such as SEZ6L, IGFBP1, which are well-established to be implicated in lung cancer development." (PMID 35768804, 2022). "Notably, the expression and function of IGFBP1 in stimulating or inhibiting lung cancer growth, as well as the detailed mechanism underlying the effect of β-elemene have yet to be elucidated." (PMID 30209296, 2018). "Stratified analysis by smoking status highlighted two proteins, IGFBP-1 and VWA1, that had stronger lung cancer risk associations in current vs former smokers (phet < 0.05)." (PMID 37264016, 2023). "In our study, we reveal the oncogenic role of IGFBP1 in lung cancer metastasis by supporting the survival of tumor cells during confined migration." (PMID 37296072, 2023). "Since IGFBP-1 has a tumor suppressor role in lung cancer, its suppression results in enhanced cancer proliferation." (PMID 35597813, 2022). "In lung cancer cells, miR-155-5p was found to downregulate the transcription factor FOXO3a, leading in turn to downregulation of IGFBP-1." (PMID 35597813, 2022). "Meanwhile, our current results reveal a regulatory axis linking FOXO3a and miR155-5p to IGFBP1, all of which have been involved in the control of biological functions, including lung cancer growth." (PMID 30209296, 2018). "Despite these findings, more experimental approaches are needed to clarify the true role of IGFBP1 in lung cancer cell biology by using stable transfection of cells with shRNA of the IGFBP1 gene in animal models." (PMID 30209296, 2018). "Our in vivo data were consistent with the findings of the in vitro study, confirming the antitumor effects of β-elemene in lung cancer and regulation of miR155-5p, FOXO3a, and IGFBP1 expression." (PMID 30209296, 2018). "Reports from our study and other studies indicated that activation of AMPK contributed to the increase in IGFBP1 and FOXO3a proteins expression, the decrease in cancer cell growth, and other functions in several cell systems including lung cancer." (PMID 27057199, 2016). "Among them, IGFBP2, IGFBP3, IGFBP4, IGFBP6 and IGFBP7 showed higher expression levels, especially in gastric, liver and lung cancer cell lines; conversely, IGFBP1, IGFBP5 and IGFBPL1 showed relatively lower expression, particularly in colorectal, gastric and kidney cancer cell lines." (PMID 37088808, 2023). "The levels of blood IGFBP1 correlate with metastatic recurrence of lung cancer patients." (PMID 37296072, 2023). "Mechanistically, we previously found that FZKA decoction could inhibit the growth of lung cancer cells through AMPKα/IGFBP1/FOXO3a, and PI3-K/Akt/NF-κB pathways, demonstrating its definite effect in treating lung cancer." (PMID 32489321, 2020). "In this study, we presented further evidence regarding protein regulation, miRNA expression, cell proliferation, and xenograft experiments in vivo to characterize the critical role of IGFBP1 as a tumor suppressor in mediating the anti-lung cancer effects of β-elemene." (PMID 30209296, 2018). "Nevertheless, our study suggests that IGFBP1 can be regarded as a potential biomarker for lung cancer survival and that increased IGFBP1 could enhance compatibility with current treatment regimens for lung cancer." (PMID 30209296, 2018). "We previously observed that ursolic acid, a natural pentacyclic triterpenoid, and emodin, a natural anthraquinone derivative isolated from the roots of Rheum palmatum, inhibited the growth of hepatocellular carcinoma and lung cancer cells by inducing IGFBP1 expression." (PMID 30209296, 2018).
lung carcinoma (continued). "Our results also indicated that the induction and interaction between IGFBP1 and FOXO3a were involved in the inhibitory responses of FAKA decoction on growth of lung cancer cells." (PMID 27057199, 2016). "Therefore, FOXO3a and SP1, as an upstream signal of Insulin‐like growth factor binding protein 1 (IGFBP1), interacted and inhibited IGFBP1 expression in A549 and PC3 cells, exerting the growth inhibitory effect of SM on lung cancer cells." (PMID 39155844, 2024).
Glucose intolerance (11 papers, 2004 to 2025). Glucose intolerance (GI) can be defined as dysglycemia that comprises both prediabetes and diabetes. "An important caveat is that total IGF-I levels were increased in IGFBP-1-KO mice, which prevents us from modelling the influence of low IGF-I and low IGFBP-1 in combination that is known to be associated with glucose intolerance in humans." (PMID 32190801, 2020). "It was found that there was an increased predisposition to develop glucose intolerance or T2D, and that this change was independent from IGFBP-1." (PMID 26733412, 2016). "Circulating IGF-I and its interaction with IGFBP-1 is crucial for glucose homoeostasis and exert a protective effect against the development of glucose intolerance." (PMID 32655494, 2020). "Whereas, mice that over-expressed human IGFBP-1 under its native promoter, only exhibit fasting hyperglycemia, hyperinsulinemia and glucose intolerance in later life." (PMID 30392760, 2019). "Circulating IGF-1 (cIGF-1) and its interactions with IGF Binding Protein 1 (IGFBP-1) are important determinants of glucose homeostasis, potentially indicating a protective role of IGF-1 against the development of glucose intolerance." (PMID 34208601, 2021). "Administration of excess IGFBP-1, or overexpression of IGFBP-1 in transgenic mice, leads to glucose intolerance and hyperinsulinaemia." (PMID 15350195, 2004). "In a prospective study (n = 922, ≥65 y, 65% F), although low IGFBP-1 was associated with increased prevalence of glucose intolerance, low IGF-I and IGFBP-3 levels, and not IGFBP-1, were associated with increased IL-6 and CRP." (PMID 39595651, 2024). "Elevated hepatic IGFBP1 may have neutralized IGF-1 in the livers of Cnot4 Het mice, leading to hepatic insulin resistance and inhibition of glucose uptake, and eventually augmenting glucose intolerance in Cnot4 Het mice." (PMID 40424271, 2025).
infertile (10 papers, 2007 to 2025). "The homeostasis of IGF-1 and IGFBP-1 clearly affects fertility, as shown by the infertility phenotype in both IGF-1-deficient mice and IGFBP-1 transgenic mice." (PMID 17201918, 2007). "In contrast, IGFBP-1 expression in infertility patients’ group was very low during all 6 days of decidualization." (PMID 34202508, 2021). "Different fasting regimens can reduce IGF-1, IGFBP1, glucose, and insulin levels and consequently have beneficial effects on ovarian function, androgen excess, and infertility in women with PCOS." (PMID 31603907, 2019). "IGFBP1 transcript levels are lower in the endometrium of sub-fertile heifers compared with highly fertile ones, a result similar to what has been observed in the endometrium of infertile women compared with fertile ones." (PMID 41004524, 2025). "Recent studies indicates that serum GdA/IGFBP-1 ratio was higher in women who achieved pregnancy compared to those who did not, and in the uterine fluid of infertile women exhibited lower concentration of GdA as compared with fertile women." (PMID 25981399, 2015). "Also, the mechanism of control over the rate of gene transcription or transcriptional regulation is altered in genes involved in chronic endometritis and the inflammatory response (IL-11, CCL4), growth factors (IGFBP1), and apoptotic proteins (BCL2, BAX, CASP8) in infertile patients." (PMID 33329514, 2020).
liver cancer (10 papers, 2012 to 2026). An epithelial or non-epithelial malignant neoplasm that arises from the liver. "Similar results were also obtained in IGFBP1‐depleted SK‐Hep1 liver cancer cells rescued with Flag‐rIGFBP1." (PMID 37296072, 2023). "More importantly, our in vivo data were consistent with the findings from that in vitro, confirming the effect of UA on liver cancer growth inhibition and regulation of IGFBP1, FOXO3a expression, and p38 MAPK phosphorylation." (PMID 27036874, 2016). "We found that SIRT2 can upregulate IGFBP1 expression and subsequently activate the PI3K/AKT/mTOR signalling pathway and that IGFBP1 is essential for the tumour-promoting function of SIRT2 in liver cancer." (PMID 42009830, 2026). "IGFBP-1, which is expressed in the liver and binds IGF-1, is regulated by HIF1α in HepsG2, a human liver cancer cell line." (PMID 32610471, 2020). "In liver cancer cells, WT1 can affect the expression of IGFBP1, which may affect the progression and cell survival." (PMID 34692659, 2021).
preeclampsia (10 papers, 2014 to 2025). Preeclampsia is a hypertensive disorder of pregnancy that is characterized by new-onset hypertension with proteinuria presenting after 20 weeks of gestation, and depending on mild or severe forms may initially present with severe headache, visual disturbances, and hyperreflexia. "IGFBP-1 has been linked to the anomalies in placental development that are seen in preeclampsia in humans." (PMID 40872670, 2025). "Insulin-like growth factor binding protein-1 (IGFBP-1) plays pathophysiological roles in preeclampsia, polycystic ovary syndrome, and trophoblastic and endometrial tumors." (PMID 40723797, 2025). "Three S100A6-interacting proteins, lumican, PRELP, and insulin-like growth factor binding protein 1 (IGFBP-1), were found in the extracellular matrix of Wharton’s jelly in healthy and preeclampsia patients." (PMID 37670392, 2023). "Likewise, the level of IGFBP1, an important marker of decidualization, in serum of preeclampsia patients was significantly lower than that of normal pregnant women before the onset of clinical symptoms but was reversed in late pregnancy." (PMID 37854606, 2023). "Lumican and PRELP exist in both healthy patients and preeclampsia patients, while IGFBP-1 only exists in the tissues of preeclampsia patients and may be associated with the development of preeclampsia." (PMID 37670392, 2023). "Additionally, data on IGFBPs and preeclampsia vary; Ingec and Giudice report higher IGFBP1 in preeclampsia, while Ning and Hietala report lower IGFBP1 in preeclampsia." (PMID 27833901, 2016). "Whereas decidual IGFBP1 production increases progressively during the first and second trimesters of uncomplicated pregnancies, women destined to develop preeclampsia present low serum levels of IGFBP1, which may indicate decidual dysfunction." (PMID 24987708, 2014). "Our results showed a decrease in the IGFBP-1 on MenSC-PE, establishing that these anomalies are related not only to impaired decidualization but also to an impaired angiogenesis, highlighting the potential importance of the cells present in the decidua in the pathogenesis of preeclampsia." (PMID 30809262, 2019). "Interestingly, a longitudinal study looking over the course of pregnancy found that compared to healthy controls, during early gestation, IGFBP1 levels were lower in women who later developed preeclampsia, but in late gestation, BP1 levels were higher than controls." (PMID 27833901, 2016). "A strong signature of dysregulated decidual gene expression (e.g., decreased levels of IGFBP1, glycodelin, PRL and IL-15) also emerged among women with severe preeclampsia compared with those experienced normal pregnancies." (PMID 37404833, 2023). "Additionally, lncRNAs like IGFBP1 and EGFR-AS1, along with protein-coding genes, impact trophoblast regulation and angiogenesis, influencing both preeclampsia and fetal growth." (PMID 38674114, 2024). "While several studies show a lack of a correlation between IGFI and/or IGFBP1 or IGFBP3 and preeclampsia, the majority report lower IGFI in women with preeclampsia." (PMID 27833901, 2016).